GSDMD (gasdermin D)
Diseases named in the same sentence as GSDMD in open-access papers (continued):
Sharing a sentence is not in itself a finding about the gene and the disease.
non-small cell lung carcinoma (continued). "GSDMD levels are dramatically increased in non-small cell lung carcinoma (NSCLC)." (PMID 40721578, 2025). "Carotenoid B triggered TLR4-induced pyroptosis via the GSDMD pathway in non-small cell lung cancer." (PMID 40756987, 2025). "Besides IL-1 family members, tumor growth can also be regulated by GSDMD, whose elevation is associated with more advanced TNM stages in non-small cell lung cancer (NSCLC) patients." (PMID 36932407, 2023). "CPI-444 71 is an immune checkpoint inhibitor used as a pyroptotic agent in non-small-cell lung carcinoma (NSCLC) and MM via caspase-1/GSDMD activation." (PMID 39316325, 2025). "GSDMD, CASP1, CASP4 and CASP5 gene expression are highly increased in PBMCs of non-small cell lung cancer patients and their expression are closely related to the clinical characteristics of patients." (PMID 37194012, 2023). "The protein levels of GSDMD were markedly upregulated in non-small cell lung cancer (NSCLC), and upregulated GSDMD was markedly correlated with invasive characteristics and worse prognosis." (PMID 36920176, 2023). "GSDMD was found to be upregulated in non-small cell lung cancer (NSCLC), knockdown of GSDMD attenuated tumor proliferation by promoting apoptosis and inhibiting EGFR/Akt signaling in NSCLC." (PMID 36189207, 2022). "Studies have shown that, in non-small cell lung cancer (NSCLC), pneumonia, and pulmonary tuberculosis, the GSDMD level was significantly upregulated." (PMID 34163438, 2021). "In non-small cell lung cancer (NSCLC), higher GSDMD expression is related to invasive features, including more advanced tumor-node-metastasis stages and larger tumor sizes." (PMID 31501419, 2019). "Further, we identified a human non-small cell lung carcinoma cell line (H1299) that does not express GSDMD." (PMID 38932190, 2024). "And the downregulation of GSDMD was found to attenuate tumor proliferation via the intrinsic mitochondrial apoptotic pathway and inhibition of EGFR/Akt signaling and predicted a good prognosis in non-small cell lung cancer." (PMID 36138348, 2022). "However, GSDMD as a pyroptosis executive protein is more highly expressed in non-small cell lung cancer (NSCLC) than para-cancer tissues, and knockdown of GSDMD can attenuate the EGFR/Akt signaling pathway to restrict tumor growth in NSCLC." (PMID 36090993, 2022). "A recent work using mouse models of non-small cell lung cancer (NSCLC) and triple-negative breast cancer (TNBC) showed that IL-1β secretion by myeloid cells was independent of inflammasome activation and gasdermin D pore formation." (PMID 35517498, 2022).
COVID-19 (37 papers, 2021 to 2026). A disease caused by infection with severe acute respiratory syndrome coronavirus 2. "Abnormal activation of GSDMD has been linked to a variety of inflammatory diseases, including non-alcoholic steatohepatitis, inflammatory bowel disease and COVID-19, and has been linked to potential pathogenesis of septic shock." (PMID 42125920, 2026). "Image analysis of lung autopsies of patients who died from COVID-19 revealed the presence of NET structures associated with activated GSDMD-NT fraction." (PMID 36830874, 2023). "Lung macrophages also showed activated inflammasomes, suggesting that GSDMD-mediated inflammatory cell death restricts viral production but causes systemic inflammation that contributes to COVID-19 pathogenesis." (PMID 35844522, 2022). "High expression of active GSDMD associated with NETs structures was found in the lung tissue of COVID-19 patients." (PMID 35799268, 2022). "For instance, high expression of GSDMD has been associated with neutrophil extracellular trap (NET) structures in the lungs of patients with COVID-19." (PMID 35587515, 2022). "The present study reveals that the virus that causes COVID-19 directly triggers NET release by a GSDMD pathway-dependent manner." (PMID 35799268, 2022). "We found that GSDMD is expressed in lung tissue of patients with severe COVID-19 in association with NETs structures." (PMID 35799268, 2022). "High expression of GSDMD is also associated with the release of neutrophil extracellular traps (NETs), a phenomenon associated with immunocoagulopathy, and organ damage found in severe COVID-19 cases." (PMID 36661317, 2023). "Moreover, the image analysis of lung autopsies from patients who died by COVID-19 showed the presence of NET structure associated with activated GSDMD-NT fraction." (PMID 35799268, 2022). "Finally, Disulfiram, the GSDMD inhibitor that covalently modifies GSDMD to block pyroptotic pore formation, was shown to associate with a lower incidence of COVID-19 in a retrospective study." (PMID 35265086, 2022). "Importantly, we observed an association between the level of cleaved GSDMD and severity of COVID-19." (PMID 35799268, 2022). "Although studies have suggested that NLPR3 activation and GSDMD serve as predictive markers for severity of COVID-19, these studies were solely conducted in vitro." (PMID 40016339, 2025). "Cellular pyroptosis is essential to the pathophysiology of COVID-19, as evidenced by the discovery of lysed GSDMD in lung tissue sections and BALF from COVID-19 patients, as well as the activation of the inflammasome by SARS-CoV-2 infection." (PMID 40593504, 2025). "It is known that Gasdermin-D (GSDMD) is a key mediator of NETosis and a study consisting of 63 hospitalized patients with moderate and severe COVID-19 revealed higher expression of GSDMD genes." (PMID 37212866, 2023). "In cell cultures of neutrophils from COVID-19 patients, disulfiram, a GSDMD inhibitor, inhibited release of NETs in a concentration-dependent manner." (PMID 36830874, 2023). "Single-cell transcriptome analysis revealed that the expression of GSDMD and inflammasome-related genes were increased in COVID-19 patients." (PMID 35799268, 2022). "To investigate the potential role of GSDMD on NETs release during COVID-19, we added disulfiram on cell cultures of neutrophils from COVID-19 patients." (PMID 35799268, 2022). "We aim to investigate the role of the Gasdermin-D (GSDMD) pathway on NETs release and the development of organ damage during COVID-19." (PMID 35799268, 2022). "There are many preclinical and clinical trials targeting NLRP3 and GSDMD to treat COVID-19 patients." (PMID 35287354, 2022). "To investigate the importance of GSDMD-dependent NETosis to COVID-19 immunopathology, we infected K18 hACE2 transgenic mice with SARS-CoV-2 and treated them with disulfiram." (PMID 35799268, 2022). "Then, we analyzed the expression of GSDMD in blood neutrophils from COVID-19 patients and healthy volunteers." (PMID 35799268, 2022).
COVID-19 (continued). "Based on our studies, it was possible that XBJ cure COVID-19 patients effectively by inhibiting NETs production, which was achieved by restraining GSDMD over-expression." (PMID 36467039, 2022). "Collectively, these findings demonstrate that pharmacological inhibition of GSDMD with disulfiram prevents NETs release and organ dysfunction and can be used to improve the COVID-19 treatment." (PMID 35799268, 2022). "The release of NETs by neutrophils infected with SARS-CoV-2 or isolated from patients with severe COVID-19 was inhibited with GSDMD inhibitor, disulfiram." (PMID 35799268, 2022). "However, we found, as a novelty, a higher degree of activation for signaling pathways related to pyroptosis and autoimmunity, like NETs formation and STING pathway in Kawasaki-like disease and COVID-19, with the involvement of the GSDMD gene." (PMID 38003837, 2023). "Therefore, SARS-CoV-2 N-protein-NLRP3 interaction and SARS-CoV-2 N-protein-GSDMD interaction act synergistically to contribute to COVID-19 pathogenesis." (PMID 36583642, 2023). "Therefore, blocking GSDMD-mediated pyroptosis and cytokine storm is a promising strategy to ameliorate severe COVID-19." (PMID 37275856, 2023). "Studies have shown that pyroptosis in COVID-19 may be associated with activation of NLRP3, ASC, and GSDMD." (PMID 36034662, 2022). "Therefore, the pharmacological inhibition of GSDMD, as with disulfiram, represents a potential strategy to improve the treatment of COVID-19." (PMID 35799268, 2022). "The role of GSDMD inhibition in COVID-19 immunopathology remains to be unraveled." (PMID 36263178, 2022). "In the present study, we identified a key role of the GSDMD pathway on NET release during COVID-19." (PMID 35799268, 2022). "Considering these findings, we investigated whether these pathways are involved in GSDMD activation in COVID-19 patients." (PMID 35799268, 2022). "Besides, SARS-CoV-2 virus directly activates the GSDMD, which induce the NETs release and lung injury in COVID-19." (PMID 36467039, 2022). "These all suggest a critical role for GSDMD in COVID-19 pathogenesis." (PMID 34899666, 2021). "SARS-CoV-2 infection could trigger the activation of NLRP3 inflammasome to release IL-1β, IL-18, and gasdermin D and, consequently, damage to lung tissue in patients with COVID-19, suggesting the dysregulation of NLRP3 inflammasome might contribute to the severity of COVID-19." (PMID 36960050, 2023). "Therefore, we propose that GSDMD is a target to ameliorate COVID-19 therapy." (PMID 35799268, 2022). "Furthermore, our DEG analysis of scRNA-seq of bronchoalveolar fluid of patients with COVID-19 showed that expression of DPP9, NLRP1, and GSDMD, an effector protein for pyroptosis, was significantly altered in Mo/Mφs of patients with severe COVID-19 compared to their moderate counterparts." (PMID 34027315, 2021). "As a part of the innate immune response to COVID-19 the NLRP3 inflammasome is generated, which stimulates the release of interleukin 1β (IL-1β), IL-18, and gasdermin D (GSDMD), ultimately leading to pyroptosis of the infected cell." (PMID 40603504, 2024). "The lung and spleen tissue obtained from patients who died from COVID-19 exhibited higher densities of cells expressing NLRP3, IL-18, NF-κB and gasdermin D, and even HMGB-1, than age-matched controls who had died unexpectedly, but free of SARS-CoV-2-infection." (PMID 38439942, 2023). "In the lung tissues of the animal model of severe COVID-19, the levels of phospho-MLKL and cleaved GSDMD, executioners of necroptosis and pyroptosis, respectively, were significantly elevated compared with the other two groups." (PMID 36507222, 2023). "We found that the SARS-CoV-2 virus directly activates the pore-forming protein GSDMD that triggers NET production and organ damage in COVID-19." (PMID 35799268, 2022).
COVID-19 (continued). "In peripheral blood immune cells and tissues of COVID-19 patients, activated NLRP3 inflammasome, caspase-1, and high levels of GSDMD-NT were found, as well as elevated expression of IL-1β and IL-18 in serum." (PMID 36532040, 2022). "Overall, our results demonstrate that CASP4/11 promotes detrimental SARS–CoV-2–induced inflammation and coagulopathy, largely independently of GSDMD, identifying CASP4/11 as a promising drug target for treatment and prevention of severe COVID-19." (PMID 35588457, 2022). "The SARS-CoV-2 infection causes inflammasome activation and pyroptosis in blood monocytes, and cleaved GSDMD was also detected in lung tissue sections and bronchoalveolar lavage fluid (BALF) patients with COVID-19." (PMID 34899666, 2021). "Oxidized phospholipids are reportedly upregulated in patients with COVID-19, and outside the context of COVID-19, they induce cytokine release in a caspase-4/11–dependent manner without requiring GSDMD-dependent cell death." (PMID 36419185, 2022). "A recent paper highlighted that antibody-opsonized respiratory syndrome coronavirus 2 (SARS-CoV-2) virions triggered inflammation and pyroptosis in human blood monocytes of patients with COVID-19 via the NLRP3/AIM2 inflammasome pathway leading to caspase-1 and GSDMD processing." (PMID 35844522, 2022). "Pharmacological inhibition of GSDMD through treatment with the inhibitor disulfiram reduces NET release and organ damage in a mouse model of SARS-CoV-2 infection, suggesting that GSDMD-dependent NETosis plays a critical role in COVID-19 immunopathology." (PMID 35587515, 2022). "Interestingly, GSDMD is highly expressed on the BALF and blood neutrophils of COVID-19 patients." (PMID 36830874, 2023). "The binding of SARS-CoV-2 N-protein to GSDMD ensures enough time for SARS-CoV-2 coronaviruses to reproduce and spread before the immune system attacks, which might explain the long asymptomatic infection of COVID-19." (PMID 36583642, 2023). "It was demonstrated that monocytes in COVID-19 patients are the outposts of SARS-CoV-2 invasion via TLR sensing and can release inflammatory cytokines by assembling NLRP3, activating caspase-1 to generate a “cytokine storm,” and synthesizing GSDMD-NT to induce cellular pyroptosis." (PMID 36532040, 2022). "The nucleocapsid binds GSDMD and hinders GSDMD processing by caspase-1, therefore these insights into how SARS-CoV-2 antagonizes cellular inflammatory responses may open new perspectives for COVID-19 treatment." (PMID 35336077, 2022). "Deficiency of caspase-11, but not GSDMD, an executioner of pyroptosis, reduces disease severity in SARS-CoV-2–infected mice, suggesting that caspase-11 (or caspase-4/5 in humans) may promote disease severity in COVID-19 independently of pyroptosis." (PMID 36419185, 2022). "Indeed, disulfiram, a drug that blocks gasdermin D (important for NET formation), reduced NET production and neutrophil infiltration to the lungs of SARS-CoV2 infected hamsters, suggesting that such therapies may be beneficial in the treatment of COVID-19." (PMID 36139476, 2022).
myocardial infarction (30 papers, 2021 to 2025). Gross necrosis of the myocardium, as a result of interruption of the blood supply to the area, as in coronary thrombosis. "The mouse myocardial I/R injury model showed that GSDMD deficiency significantly reduced I/R-induced myocardial infarct size." (PMID 35509275, 2022). "As an executive protein of pyroptosis, GSDMD deficiency prevents cell destruction and releases inflammatory mediators, thereby ameliorating myocardial infarction." (PMID 35783187, 2022). "In addition, GSDMD axis is deeply associated with OS and pyroptosis of myocardial cells in myocardial infarction." (PMID 36988259, 2023). "Circulating GSDMD levels are elevated in patients with acute myocardial infarction and heart failure, correlating with infarct size and inflammatory cytokine profiles." (PMID 40832143, 2025). "zDHHC14 catalyzes Spalmitoylation of GSDMD at Cys192, fostering pore formation and accelerating pyroptotic cardiomyocyte death during acute myocardial infarction." (PMID 40898242, 2025). "Inhibition of GSDMD can reduce the area of myocardial infarction, exerting a cardioprotective function." (PMID 39301029, 2024). "During myocardial infarction, upregulated CXCR4 activates the NF-κB/GSDMD axis to cause damage to cardiomyocytes and impair heart function." (PMID 39253076, 2024). "In fact, a relationship between GSDMD and granulopoiesis has been reported in myocardial infarction (MI), albeit in the opposite direction, with GSDMD promoting granulopoiesis through the NLRP3-GSDMD-IL-1β signaling pathway." (PMID 38831451, 2024). "Most recently, Gasdermin D(GSDMD)-mediated cardiomyocyte pyroptosis was reported to contribute toward heart damage during myocardial infarction and reperfusion injury." (PMID 35432334, 2022). "In addition, macrophage-derived EVs enriched in miR-378a-3p have been shown to regulate cell death by blocking activation of the NLRP3/Caspase-1/GSDMD pathways in cardiomyocytes after myocardial infarction." (PMID 40496017, 2025). "The GSDMD, as a key mediator of cell pyroptosis, is closely associated not only with pathological process in SLE but also with the inflammatory response during acute myocardial infarction." (PMID 39301029, 2024). "Pyroptosis and apoptosis occur in myocardial ischemia reperfusion (I/R) and myocardial infarction (MI), and GSDMD plays an important role in I/R, MI, and atherosclerosis." (PMID 36289195, 2022). "Clinical myocardial samples have demonstrated pronounced co-localisation of PCSK9 with N-terminal gasdermin D (GSDMD-NT) in the peri-infarct zone, implicating PCSK9 in pyroptotic injury during acute myocardial infarction." (PMID 41008547, 2025). "Conversely, inhibiting the production of NLRP3 inflammasome or GSDMD induced pyroptosis can reduce MIRI and myocardial infarction size." (PMID 35571159, 2022). "The myocardial infarction area was significantly reduced in rats with myocardial infarction injected with KLF3-AS1 exosome, and the expressions of NLRP3, caspase-1, GSDMD, IL-1β and IL-18 in KLF3-AS1-overexpressed myocardial infarction mice were also significantly decreased." (PMID 37396588, 2023). "The results from that study indicated that cinnamyl ethyl acetate extract reduced the size of myocardial infarction, improved myocardial function, and reduced the level of ASC, IL-1β, caspase-1, and GSDMD, and suppressed the expression of inflammatory factors in N-terminal GSDMD." (PMID 36291138, 2022).